RNU6-712P (RNA, U6 small nuclear 712, pseudogene)
Gene: Small nuclear RNA gene on chromosome 3 (90,184,634 to 90,184,733, forward strand). Ensembl gene ENSG00000222490.
Homologues: Orthologues: chimpanzee U6 (99% identical), guinea pig U6 (70% identical). Paralogues in human: RNU6-488P (92% identical), RNU6-98P (83% identical), RNU6-1094P (81% identical), RNU6-1083P (80% identical), RNU6-1091P (80% identical), RNU6-11P (80% identical), RNU6-1243P (80% identical), RNU6-1287P (80% identical), RNU6-24P (80% identical), RNU6-272P (80% identical), RNU6-37P (80% identical), RNU6-12P (79% identical), and 1284 more.